LOXL2 (lysyl oxidase like 2)
Diseases named in the same sentence as LOXL2 in open-access papers (continued):
Sharing a sentence is not in itself a finding about the gene and the disease.
non-small cell lung carcinoma (7 papers, 2020 to 2025). A group of at least three distinct histological types of lung cancer, including non-small cell squamous cell carcinoma, adenocarcinoma, and large cell carcinoma. "High expression of LOX and LOXL2 mRNA and protein is for the most part associated with poor prognosis in non-small cell lung cancer (NSCLC) patients." (PMID 35205728, 2022). "MiR-504 is another tumour-suppressive miRNA that targets LOXL2 mRNA in non-small cell lung cancer cell lines." (PMID 37762708, 2023). "In patients with non-small cell lung cancer (NSCLC), the expression levels of PLOD1–3 and LOXL2—genes involved in collagen crosslinking—are significantly elevated in TECs compared to normal endothelial cells." (PMID 40721833, 2025). "An in vivo study of non-small cell lung carcinoma (NSCLC) showed that downregulation of LOXL2 accelerated disease progression and, when examining tumours from patients, higher stage disease was correlated with low LOXL2 expression." (PMID 33513979, 2021). "In non-small cell lung cancer (NSCLC), miR-504 has been reported to function as a tumor-suppressing factor by directly targeting the 3′UTR of LOXL2." (PMID 33371259, 2020).
osteosarcoma (7 papers, 2020 to 2026). A usually aggressive malignant bone-forming mesenchymal neoplasm, predominantly affecting adolescents and young adults. "By elucidating the role of these pathways in mediating LOXL2-driven osteosarcoma metastasis, this study provides a deeper understanding of the molecular interplay underlying osteosarcoma progression." (PMID 41399365, 2026). "In this study, we sought to identify a mechanistic link between FGF-23 and the metastatic behavior of osteosarcoma cells, focusing on the miR-4463/LOXL2 axis and its effects in regulating the ERK, p38, and JNK signaling pathway." (PMID 41399365, 2026). "In vitro experiments confirmed that treatment of osteosarcoma cells with FGF-23 increased LOXL2 mRNA and protein expression in a dose-dependent manner, while the effects on LOXL1 and LOXL3 were comparatively limited." (PMID 41399365, 2026). "In the present study, we demonstrated that the growth factor FGF-23 activates ERK, p38, and JNK signaling, leading to upregulation of LOXL2 and enhanced migratory capacity of osteosarcoma cells." (PMID 41399365, 2026). "Together, these findings provide strong evidence that FGF-23 promotes osteosarcoma cell migration by specifically upregulating LOXL2 expression." (PMID 41399365, 2026). "In the present study, pretreatment of osteosarcoma cells with a miR-4463 mimic reversed FGF-23-mediated LOXL2 expression downstream of ERK, p38, and JNK signaling, and suppressed the enhanced migratory ability of osteosarcoma cells in vitro." (PMID 41399365, 2026). "Pretreatment with specific inhibitors or siRNAs targeting ERK, p38, and JNK effectively suppressed FGF-23-induced LOXL2 expression and reduced osteosarcoma cell migration." (PMID 41399365, 2026). "Our results demonstrated that FGF-23 promotes LOXL2 expression and enhances osteosarcoma cell migration through activation of ERK, p38, and JNK signaling pathways, while simultaneously inhibiting miR-4463 expression." (PMID 41399365, 2026). "In vitro experiments further showed that FGF-23 significantly upregulates LOXL2 expression in 143B and MG63 osteosarcoma cells, while LOXL2 knockdown via small interfering RNA (siRNA) markedly reduces cell migration." (PMID 41399365, 2026). "Experimental validation demonstrated that FGF-23 significantly downregulates miR-4463 expression while upregulating LOXL2, thereby promoting osteosarcoma cell migration." (PMID 41399365, 2026). "In conclusion, this study demonstrates that FGF-23 promotes the migration and metastatic potential of osteosarcoma cells by upregulating LOXL2 expression through the suppression of miR-4463." (PMID 41399365, 2026). "Wound healing assays further demonstrated that FGF-23 enhanced osteosarcoma cell migration, an effect that was significantly inhibited by LOXL2 siRNA transfection." (PMID 41399365, 2026). "In this study, we investigated the role of miRNAs in FGF-23-induced LOXL2 expression and osteosarcoma cell migration." (PMID 41399365, 2026). "In summary, this study demonstrates that FGF-23 suppresses miR-4463 synthesis through the ERK, p38, and JNK signaling cascade, thereby facilitating LOXL2-dependent migration in osteosarcoma cells." (PMID 41399365, 2026). "Our findings suggest that FGF-23 promotes osteosarcoma cell migration and metastasis by upregulating LOXL2 expression via activation of the ERK, p38, and JNK signaling pathways." (PMID 41399365, 2026). "METTL1 stimulates osteosarcoma malignancy by augmenting mRNA translation of lysyl oxidase‐like 2 (LOXL2), a key downstream target of METTL1 that is required for its function in osteosarcoma." (PMID 39979979, 2025). "DHA significantly inhibited osteosarcoma cell proliferation, migration, and invasion and induced apoptosis through the downregulation of LOXL2 expression." (PMID 37762708, 2023). "Molecular pathways downstream of Wnt ligands play a critical role in tumorigenesis and are evolutionarily conserved, and Wnt signaling and Loxl2 promote aggressive osteosarcoma." (PMID 36428766, 2022).
osteosarcoma (continued). "In addition, WNT7B and WNT9A signaling pathways have been shown to enhance LOXL2 expression, further supporting its role in promoting osteosarcoma proliferation and metastasis." (PMID 41399365, 2026). "Investigating the interplay between FGF-23 and LOXL2 in osteosarcoma may provide new mechanistic insights and identify potential therapeutic targets to inhibit malignant progression and improve clinical outcomes." (PMID 41399365, 2026). "Elucidating the pathways that regulate LOXL2 expression may offer a promising direction for developing targeted therapies against osteosarcoma metastasis." (PMID 41399365, 2026). "Taken together, these findings suggest that FGF-23 promotes osteosarcoma cell migration and may contribute to metastasis through coordinated regulation of the miR-4463/LOXL2 axis via ERK, p38, and JNK signaling." (PMID 41399365, 2026). "Furthermore, the bone ECM provides a supportive niche for osteosarcoma metastasis, where elevated LOXL2 expression contributes to increased matrix stiffness and enhanced cell-matrix adhesion." (PMID 41399365, 2026). "Furthermore, pretreatment with ERK, p38, and JNK inhibitors or siRNAs reversed the FGF-23-induced suppression of miR-4463 and the increase in LOXL2 expression, indicating that the FGF-23/miR-4463/LOXL2 axis contributes to the regulation of osteosarcoma metastasis." (PMID 41399365, 2026). "However, in clear cell renal cell carcinoma, the lncRNA myocardial infarction-associated transcript (MIAT) binds to and inhibits miR-29c action on LOXL2, while in osteosarcoma, the lncRNA human major histocompatibility complex p5 (HCP5) neutralises the action of miR-29b." (PMID 37762708, 2023). "Gene Expression Omnibus (GEO) analysis indicated that lysyl oxidase-like proteins—particularly LOXL1, LOXL2, and LOXL3—are overexpressed in osteosarcoma tissues compared to adjacent normal bone." (PMID 41399365, 2026). "Analysis of the GEO database revealed that LOXL1, LOXL2, and LOXL3 expression levels were significantly elevated in osteosarcoma tissue samples compared to normal bone, indicating their involvement in disease progression." (PMID 41399365, 2026). "In our study, wound healing and qPCR assays showed that pretreatment of osteosarcoma cells with ERK, p38, or JNK inhibitors—or siRNAs targeting ERK, p38, or JNK—significantly reduced FGF-23-induced cell migration and LOXL2 expression." (PMID 41399365, 2026). "Taken together, these findings suggest that FGF-23 exerts a pro-metastatic effect in osteosarcoma through ERK-, p38-, and JNK-mediated regulation of the miR-4463/LOXL2 axis." (PMID 41399365, 2026).
pancreatic ductal adenocarcinoma (7 papers, 2019 to 2026). An infiltrating adenocarcinoma that arises from the epithelial cells of the pancreas. "LOXL2 overexpression has also been shown to promote the growth of both primary and metastatic pancreatic ductal adenocarcinoma and to reduce survival in mouse models." (PMID 41399365, 2026). "We studied whether SP1 exerts its effect on invasiveness and promotion of the epithelial-mesenchymal transition (EMT) by regulating lysyl oxidase-like 2 (LOXL2) in pancreatic ductal adenocarcinoma (PDAC) cell lines." (PMID 30976063, 2019). "Contradictorily, in pancreatic ductal adenocarcinoma, decreasing ECM with an anti-LOXL2 antibody in vivo boosted tumor growth and diminished overall survival, suggesting a protective role of ECM." (PMID 34646782, 2021). "However, in pancreatic ductal adenocarcinoma, the ECM is also a protective factor, as demonstrated by impairing ECM with an anti-lysyloxidase-like 2 (LOXL2) antibody in vivo, hence accelerating tumor progression and decreasing overall survival (OS)." (PMID 35911730, 2022). "Intriguingly, in pancreatic ductal adenocarcinoma, decreasing ECM with an anti–lysyl oxidase like-2 (anti-LOXL2) antibody in syngeneic orthotopic PDA mouse models accelerated tumor growth, resulting in diminished overall survival, which suggested a protective role of ECM." (PMID 34646782, 2021).
Cirrhosis (6 papers, 2018 to 2025). A chronic disorder of the liver in which liver tissue becomes scarred and is partially replaced by regenerative nodules and fibrotic tissue resulting in loss of liver function. "Anti-LOXL2 therapies: Lysyl oxidase-like 2 (LOXL2) inhibitors are being investigated for their ability to diminish extracellular matrix remodeling in cirrhosis." (PMID 40430206, 2025).
diabetes (6 papers, 2019 to 2026). "Regarding metabolic disorders, our study confirmed that a pre-Tx diagnosis with diabetes mellitus was an independent risk factor along with serum LOXL2 levels; however, the number of patients who were positive for both parameters was too small (N = 5) for evaluation." (PMID 38740815, 2024). "Interestingly, the combinations of serum LOXL2 levels ≥ 2.08 ng/mL with a platelet count < 120 × 109/L, age ≥ 65 years, or a diagnosis with diabetes mellitus were identified as independent risk factors in the multivariate analysis, but effective risk stratification was not achieved." (PMID 38740815, 2024). "Combinations of serum LOXL2 levels with serum AFP level, platelet count, age, and presence of diabetes mellitus, were identified as independent risk factors for post-SVR HCC development." (PMID 38740815, 2024). "The observed increase at 11 weeks of LOXL2 expression was confirmed by various other HF studies other than diabetes, where the authors showed an increase in mRNA expression of LOXL2 was positively correlated with increased tissue fibrosis." (PMID 32703998, 2020). "Collectively, these findings establish endothelial LOX/LOXL2 as core regulators of pathogenic glomerular signaling in diabetes and position Verbascoside as an enzymatically targeted precision therapy for DKD acting through the disruption of this specific LOX/LOXL2-mediated axis." (PMID 41355449, 2025). "A logistic regression model including time since transplantation, IFTA, hypertension/diabetes status (HTN/DM), and mean LOXL2+ cells in the biopsy was applied in non rejection biopsies to predict a 0.5 mg/dl increase of the baseline creatinine." (PMID 41607781, 2026).
primary sclerosing cholangitis (6 papers, 2019 to 2026). "Interestingly, the serum levels of LOXL2 are significantly higher in primary sclerosing cholangitis (PSC), which is closely associated with IBD, and LOXL2 targeting in IBD has been evaluated in PSC." (PMID 34211502, 2021). "However, a humanized anti-LOXL2 antibody Simtuzumab did not demonstrate a clinical benefit in patients with primary sclerosing cholangitis and NASH." (PMID 37328872, 2023).
prostate tumor (6 papers, 2016 to 2025). "LOXL2 derived by cancer‐associated fibroblasts has also been confirmed to be an important mediator of intercellular communication in prostate tumor." (PMID 32970930, 2020). "We present the first data showing that the inhibition of LOXL2 in prostate CAF can significantly perturb the prostate tumor microenvironment." (PMID 31061140, 2019). "Our data provide the first demonstration that prostate CAF-dependent LOXL2 production controls prostate tumor cell motility, highlighting LOXL2 as an attractive therapeutic target." (PMID 31061140, 2019). "It has been previously demonstrated that CAF-derived LOXL2 is an important mediator of intercellular communication in the prostate tumor microenvironment and may be useful as a potential therapeutic target." (PMID 36937411, 2023). "Using a proteomic strategy based on this concept, our global proteomic analysis of CAF established from primary prostate tumors identified a prominent protein-protein interaction hub centered on the DDR2-collagen-LOXL2 signaling axis, critical for ECM remodeling and function." (PMID 31061140, 2019). "Combined, these data indicate that LOX/LOXL2 production by prostate CAF produces a highly aligned ECM that can potentiate the migration of CAF themselves, as well as neighboring prostate tumor cells." (PMID 31061140, 2019). "Pre-treatment of CAF with the LOXL2 inhibitor DPEN significantly impaired the mean speed and track length of co-cultured RWPE-2 prostate tumor cells in all patients tested (Patient 4–6)." (PMID 31061140, 2019). "Because CAF also regulate the migration ability of prostate tumor epithelium, we next assessed the potential paracrine role of LOX/LOXL2 secreted by CAF." (PMID 31061140, 2019).
renal cell carcinoma (6 papers, 2016 to 2022). "For instance, in renal cell carcinoma, miR-29 can inhibit the migration and invasion of RCC cells in vitro by negatively regulating the expression of LOXL2." (PMID 32192508, 2020). "In renal cell carcinoma (RCC), miR-26a/b overexpression exhibits inhibitory efficacy on cancer cell proliferation, migration, and invasion through the direct binding of 3′UTR of LOXL2 mRNA." (PMID 33371259, 2020).
renal fibrosis (6 papers, 2018 to 2026). A final common manifestation of a wide variety of chronic kidney diseases characterized by glomerulosclerosis and tubulointerstitial fibrosis. "IFN-γ treatment increased Trim21 expression, reduced Loxl2 expression and renal fibrosis; critically, this protective effect was abolished in tubular-specific Trim21 knockout mice." (PMID 42129148, 2026). "In relatively mild renal fibrosis models such as in diabetic glomerulosclerosis or cyclosporine-induced renal interstitial fibrosis, LOXL2 inhibition alone is sufficient to ameliorate the progress of fibrosis." (PMID 35628342, 2022). "LOXL-2 crosslinks collagens and elastin resulting in increased ECM stiffness and has been associated with renal fibrosis and pathology." (PMID 33748219, 2021). "Lysyl oxidase-like 2 (LOXL2) is elevated in renal fibrosis and known to play key roles in ECM stabilisation by facilitating collagen cross-links, epithelial to mesenchymal transition and myofibroblast activation." (PMID 29930330, 2018). "The expression pattern of LOXL2 in focal areas of strong tubular damage as well as de-novo expression in diseased glomeruli suggests its direct involvement in the renal fibrosis process." (PMID 29930330, 2018). "The present study aims to explore the role of LOXL2 in a renal fibrosis model of diabetic nephropathy and examined the therapeutic potential of PXS-S2B as a renoprotective small molecule." (PMID 29930330, 2018). "Similar to these results, previous studies also reported the overexpression of LOX and LOXL-2 in various pathological conditions characterized by fibrotic phenotypes, including IPF, renal fibrosis, cardiac fibrosis, skin aging and systemic sclerosis." (PMID 33672186, 2021). "Thus, we suggest that the inhibition of FA-induced renal fibrosis by AD-114 is at least partially mediated by antagonizing TGF-β1 and LOXL2." (PMID 35015734, 2022). "The known multifaceted action of LOXL2 on ECM synthesis involving cross-linking of collagens, myofibroblast activation and stimulation of increased matrix products makes it a promising target in diabetic kidney fibrosis and possibly renal fibrosis of other aetiologies." (PMID 29930330, 2018). "Despite the known involvement of LOXL2 in a variety of processes that affect ECM deposition and enhance fibrosis, its role as a potential treatment target in renal fibrosis is not well studied." (PMID 29930330, 2018).
triple-negative breast carcinoma (6 papers, 2016 to 2025). An invasive breast carcinoma which is negative for expression of estrogen receptor (ER), progesterone receptor (PR), and human epidermal growth factor receptor 2 (HER2). "Increased expression of LOXL2 also results in reduced chemosensitivity in triple-negative breast cancer." (PMID 36620542, 2022). "LOXL2 expression correlates with IDC cell aggressiveness, as the more aggressive MDA-MB-231 and MDA-MB-468 triple negative breast cancer cell lines show higher LOXL2 expression than less aggressive ER+/PR+ MCF7 cells." (PMID 34011405, 2021). "Levels of PEAR1 protein and PEAR1 phosphorylation at Ser891 were increased in patients with triple-negative breast cancer (TNBC), were positively correlated with expression of LOXL2 and CD44, and were negatively correlated with overall survival." (PMID 39145451, 2024).
clear cell renal cell carcinoma (5 papers, 2017 to 2024). "Whereas, LOXL2 knockdown markedly reduces stress fiber and focal adhesion formation in human clear cell renal cell carcinoma cells." (PMID 28556501, 2017). "Furthermore, integrin β1 or β3 mediated mechanotransduction is correlated with LOX expression in clear cell renal cell carcinoma and LOXL2 expression in fibroblasts, respectively, and is known to activate the FAK/Src or PI3K/Akt signaling pathways." (PMID 33513979, 2021). "Increases in LOX, LOXL2 and LOXL4 expression in the ECM of cancer is linked to an increase in focal adhesion kinase (FAK) and Src phosphorylation in colorectal adenocarcinoma, gastric cancer, clear cell renal cell carcinoma and fibroblasts." (PMID 33513979, 2021). "In contrast, LOXL2 knockdown decreases integrin α5 activation of JNK signaling and results in reduced cell migration and focal adhesion formation in human clear cell renal cell carcinoma." (PMID 33513979, 2021). "The effect of LOXL2 on upregulating ITGB1 expression via inhibiting degradation of ITGB1 protein by proteasome pathway has been reported in clear cell renal cell carcinoma, however the authors did not do any further studies to investigate the interactions of the two proteins." (PMID 38326908, 2024).